POLRMT (RNA polymerase mitochondrial)
Description:
DNA-dependent RNA polymerase catalyzes the transcription of mitochondrial DNA into RNA using the four ribonucleoside triphosphates as substrates. Component of the mitochondrial transcription initiation complex, composed at least of TFB2M, TFAM and POLRMT that is required for basal transcription of mitochondrial DNA. In this complex, TFAM recruits POLRMT to a specific promoter whereas TFB2M induces structural changes in POLRMT to enable promoter opening and trapping of the DNA non-template strand. Has DNA primase activity. Catalyzes the synthesis of short RNA primers that are necessary for the initiation of lagging-strand DNA synthesis from the origin of light-strand DNA replication (OriL).
Synonyms: MtRPOL; h-mtRPOL; APOLMT; MTRNAP; COXPD55
Tractability: Small molecule: a structure with a bound ligand is known; it has a binding pocket of medium quality. PROTAC: ubiquitination databases record sites on it; its protein half-life has been measured.
Target class: Enzyme; Transferase
Gene: Protein-coding gene on chromosome 19 (617,168 to 633,572, reverse strand). Ensembl gene ENSG00000099821.
Subcellular location: Mitochondrion
Subcellular location (Human Protein Atlas): Mitochondria
Pathways (Reactome):
DNA Replication: Strand-asynchronous mitochondrial DNA replication
Gene expression (Transcription): Mitochondrial transcription initiation
Organelle biogenesis and maintenance: Transcriptional activation of mitochondrial biogenesis
Gene Ontology:
Molecular function: 3'-5'-RNA exonuclease activity; DNA-directed RNA polymerase activity; protein binding; RNA binding; sequence-specific DNA binding; mitochondrial promoter sequence-specific DNA binding; 5'-3' RNA polymerase activity; DNA binding
Biological process: mitochondrial transcription; transcription initiation at mitochondrial promoter; mitochondrial DNA replication; DNA-templated transcription
Cellular component: mitochondrial matrix; mitochondrial nucleoid; mitochondrion; protein-containing complex; mitochondrial DNA-directed RNA polymerase complex
Genetic constraint (gnomAD): Loss-of-function variants: 117 observed, 108.27 expected, observed/expected ratio (o/e) 1.08, 90% interval 0.93 to 1.26. The synonymous counts are far from expectation, so gnomAD's model fits this gene poorly and the ratio says little. Missense variants: 2,000 observed, 1,530.7 expected, observed/expected ratio (o/e) 1.31, 90% interval 1.26 to 1.36. Synonymous variants: 1,020 observed, 685.52 expected, observed/expected ratio (o/e) 1.49, 90% interval 1.41 to 1.57.
Homologues: Orthologues: chimpanzee POLRMT (98% identical), macaque POLRMT (88% identical), dog POLRMT (71% identical), pig POLRMT (70% identical), mouse Polrmt (66% identical), rat Polrmt (64% identical), guinea pig POLRMT (61% identical), tropical clawed frog polrmt (46% identical), zebrafish polrmt (45% identical), Drosophila melanogaster PolrMT (39% identical), Caenorhabditis elegans rpom-1 (26% identical).
Diseases named in the same sentence as POLRMT in open-access papers:
POLRMT is named in the same sentence as 46 diseases in open-access papers, as found by Europe PMC text mining. Sharing a sentence is not in itself a finding about the gene and the disease. The quoted sentences say what the papers report.
osteosarcoma (8 papers, 2022 to 2025). A usually aggressive malignant bone-forming mesenchymal neoplasm, predominantly affecting adolescents and young adults. "A growing body of evidence indicates that POLRMT expression is associated with various cancers, including skin squamous cell carcinoma, osteosarcoma, acute myeloid leukemia, and breast cancer." (PMID 37283308, 2023). "Han and colleagues demonstrated that elevated POLRMT levels were essential for the in vitro growth of osteosarcoma cells and the development of osteosarcoma xenografts in nude mice." (PMID 38907279, 2024). "The depletion of POLRMT using genetic means resulted in mitochondrial dysfunction, energy depletion, and apoptosis in osteosarcoma cells." (PMID 38907279, 2024). "Whereas POLRMT depletion hindered osteosarcoma cell proliferation and migration in vitro, and inhibited osteosarcoma xenograft growth in nude mice." (PMID 36823110, 2023). "Contrarily, shRNA-mediated silencing or CRISPR/Cas9-induced knockout (KO) of POLRMT potently suppressed osteosarcoma cell growth in vitro and in vivo." (PMID 37816734, 2023). "Besides the role of POLRMT in NSCLC, recently published studies have revealed the protumoral role of POLRMT in skin squamous cell carcinoma, osteosarcoma, acute myeloid leukemia, and breast cancer." (PMID 37283308, 2023). "The mtDNA contents, mitochondrial transcripts, and respiratory chain complex subunits were all downregulated in POLRMT-depleted NSCLC cells and osteosarcoma cells." (PMID 37816734, 2023). "To this end, we evaluated the viability of the human osteosarcoma 143B cells after inactivating TFAM, POLRMT, TFB2M, POLG, POLG2, or SSBP1 with CRISPR-Cas9." (PMID 35883613, 2022).
acute myeloid leukemia (5 papers, 2016 to 2023). Acute myeloid leukemia (AML) is a group of neoplasms arising from precursor cells committed to the myeloid cell-line differentiation. "In acute myeloid leukemia (AML) cells shRNA-induced knockdown of POLRMT reduced oxidative phosphorylation (OXPHOS), cell growth and viability." (PMID 34907167, 2021). "Additionally, JQ1 treatment of the primary human fibroblast line LG1 and the acute myeloid leukemia cell line NOMO-1, the cell lines used to originally characterize the effect of JQ1 on MYC expression, led to decreased levels of POLRMT mRNA." (PMID 27590350, 2016). "POLRMT silencing largely inhibited OXPHOS and hindered acute myeloid leukemia (AML) cell growth." (PMID 36823110, 2023).
breast cancer (5 papers, 2015 to 2023). A primary or metastatic malignant neoplasm involving the breast. "Additionally, overexpression of POLRMT increased the metabolic rate of breast cancer cells and promoted tumor growth in vivo, showing its tumorigenic properties." (PMID 33923185, 2021). "Moreover, recombinant over-expression of mitochondrial-related proteins, such as PGC1-alpha/beta, POLRMT, MitoNEET or GOLPH3, is sufficient to promote tumor growth, by up to 3-fold, in xenografted pre-clinical models of human breast cancers." (PMID 26421711, 2015).
skin squamous cell carcinoma (5 papers, 2023 to 2024). A carcinoma arising from the squamous cells of the epidermis. "This POLRMT inhibitor has been shown to compromise mitochondrial functions and impede the growth of various cancer cell types, including endometrial carcinoma cells and skin squamous cell carcinoma cells." (PMID 38907279, 2024).
endometrial carcinoma (4 papers, 2023 to 2024). A malignant tumor arising from the epithelium that lines the cavity of the uterine body. "Genetic evidences supported that shRNA-induced silencing or CRISPR/Cas9-caused KO of POLRMT similarly induced robust anti-cancer cell activity in cultured endometrial carcinoma cells." (PMID 36823110, 2023). "The POLRMT-overexpressing lentivirus was also added to the immortalized cell lines (HEC-1/KLE) or other primary endometrial carcinoma cells (“phEC-2/phEC-3”)." (PMID 36823110, 2023). "mtDNA transcription and ATP contents were however increased in POLRMT-overexpressed endometrial carcinoma cells." (PMID 36823110, 2023). "The current study explored the potential anti-endometrial carcinoma activity by a first-in-class POLRMT (RNA polymerase mitochondrial) inhibitor IMT1." (PMID 36823110, 2023). "Contrarily, ectopic overexpression of POLRMT further augmented proliferation and motility of primary endometrial carcinoma cells." (PMID 36823110, 2023). "Ectopic overexpression of POLRMT augmented cell proliferation (EdU assays) and in vitro cell migration in the immortalized and primary endometrial carcinoma." (PMID 36823110, 2023). "Conversely, ectopic overexpression of POLRMT, by the lentiviral construct, further augmented endometrial carcinoma cell proliferation and motility." (PMID 36823110, 2023). "A very recent study discovered that POLRMT inhibition by IMT1 resulted in mtDNA transcription inhibition, mitochondrial oxidative injury, energy stress, and ATP loss in endometrial carcinoma cells." (PMID 37816734, 2023). "It is likely that POLRMT inhibition/silencing only targeted the enhanced mitochondrial functions (including OXPHOS) in endometrial carcinoma cells, this explains the ineffectiveness of IMT-1 treatment/POLRMT silencing in primary endometrial epithelial cells." (PMID 36823110, 2023). "Similar observations were obtained with IMT1, where inhibiting POLRMT activity in breast or endometrial cancer prevented cell proliferation and induced apoptosis in only a small percentage of the cell population." (PMID 37371693, 2023). "POLRMT is overexpressed at both the mRNA and protein level in several cancers, including breast, skin, lung, endometrial cancer, and osteosarcomas." (PMID 37371693, 2023). "Similarly, POLRMT depletion, through shRNA-induced silencing or CRISPR/Cas9-caused knockout (KO), inhibited primary endometrial carcinoma cell proliferation and motility, and induced mitochondrial dysfunction and apoptosis." (PMID 36823110, 2023). "Thus, targeting POLRMT by IMT1 potently inhibited endometrial carcinoma cell growth in vitro and in vivo." (PMID 36823110, 2023). "Here the results of the present study supported that POLRMT could be an important therapeutic target of endometrial carcinoma." (PMID 36823110, 2023). "Since POLRMT inhibition by IMT1 induced robust anti-endometrial carcinoma cell activity, we further hypothesized that POLRMT depletion should exert the similar actions." (PMID 36823110, 2023). "The POLRMT inhibitor potently inhibited cell viability and reduced CCK-8 OD in the primary and established endometrial carcinoma cells." (PMID 36823110, 2023). "Importantly, IMT1 failed to induce further cytotoxicity in POLRMT-KO endometrial carcinoma cells." (PMID 36823110, 2023).
leukemia (4 papers, 2015 to 2026). A malignant (clonal) hematologic disorder, involving hematopoietic stem cells and characterized by the presence of primitive or atypical myeloid or lymphoid cells in the bone marrow and the blood. "Importantly, succinyl-CoA level and POLRMT succinylation are downregulated in FLT3-mutated clinical leukemia samples, linking enhanced mitobiogenesis to cancer progression." (PMID 38649537, 2024). "AML-derived mutations of FMS-like tyrosine kinase 3 (FLT3) upregulated SUCLG1 to induce POLRMT hyposuccinylation, resulting in enhanced mitobiogenesis and leukemia progression." (PMID 38649537, 2024). "Re-introduction of wild-type POLRMT or POLRMTK622R in POLRMT-knockdown cells restored leukemia progression to a similar level." (PMID 38649537, 2024). "Specifically, leukemia-promoting FMS-like tyrosine kinase 3 (FLT3) mutations modulate nuclear transcription and upregulate SUCLG1 expression to reduce succinyl-CoA and POLRMT succinylation, resulting in enhanced mitobiogenesis." (PMID 38649537, 2024). "Given that mitochondrial respiration is indispensable to leukemic growth, we investigated the pathophysiological function of POLRMT succinylation in leukemia cells." (PMID 38649537, 2024). "SUCLG1-mediated POLRMT hyposuccinylation maintains mtDNA transcription, mitochondrial biogenesis, and leukemia cell proliferation." (PMID 38649537, 2024). "So far, it was proven to be overexpressed in hematological malignancies, and knockdown of POLRMT expression significantly inhibited the growth of leukemia cells, mitochondrial complex I activity, and oxidative phosphorylation without affecting the cell cycle." (PMID 33923185, 2021). "POLRMT-knockdown cells and leukemia cells treated with 2-CM showed a decrease in oxidative phosphorylation." (PMID 26484416, 2015). "Our data suggest that dysregulated POLRMT activity upregulates the expression of key respiratory chain proteins, increasing mitochondrial function and helping to fuel uncontrolled growth of the leukemia." (PMID 41498402, 2026). "SUCLG1 may have functions other than modulating POLRMT succinylation to support leukemia cell proliferation." (PMID 38649537, 2024). "Together, SUCLG1 and POLRMT are essential for mutant FLT3-driven leukemia." (PMID 38649537, 2024). "In line, genetic depletion of POLRMT or SUCLG1 significantly delays disease progression in mouse and humanized leukemia models." (PMID 38649537, 2024).
non-small cell lung carcinoma (3 papers, 2016 to 2024). A group of at least three distinct histological types of lung cancer, including non-small cell squamous cell carcinoma, adenocarcinoma, and large cell carcinoma. "In the non-small cell lung cancer cell line H1299, depletion of MYC via shRNA led to a decrease in POLRMT protein." (PMID 27590350, 2016).
colon carcinoma (2 papers, 2016 to 2024). "Quantitative analysis encompassing data from all twenty patients confirmed a significant elevation of POLRMT protein in colon cancer tissues compared to normal tissues (P < 0.05 versus “N” tissues)." (PMID 39227564, 2024). "Treatment with the POLRMT inhibitor also disrupted mitochondrial functions in other primary colon cancer cells (pCan2 and pCan3) and immortalized HCT116 cells." (PMID 39227564, 2024). "The same lentiviral construct was utilized to over-express POLRMT (“oePOLRMT”) in other primary colon cancer cells (pCan2 and pCan3) and immortalized HCT116 cells." (PMID 39227564, 2024). "Both POLRMT mRNA and protein levels were notably higher in the primary colon cancer cells (“pCan1” and “pCan2”) in comparison to levels observed in primary human colon epithelial cells (“pEpi1” and “pEpi2”)." (PMID 39227564, 2024). "Furthermore, analysis of colon cancer tissues from four representative patients (Patient-1# to Patient-4#) demonstrated an upregulation of POLRMT protein." (PMID 39227564, 2024). "For this purpose, HCT116 colon carcinoma cells, which express high levels of endogenous MYC, were depleted of POLRMT, MYC, or both POLRMT and MYC using shRNA." (PMID 27590350, 2016). "Importantly, treatment with IMT1 or silencing POLRMT in primary colon cancer cells decreased the phosphorylation of Akt1-S6K1, whereas overexpression of POLRMT had the opposite effect." (PMID 39227564, 2024).
colorectal cancer (2 papers, 2016 to 2024). A primary or metastatic malignant neoplasm that affects the colon or rectum. "Similarly, several cancer types including colorectal cancers, diffuse large B cell lymphoma, and multiple myeloma display increased POLRMT expression correlated with increased MYC expression in cancer cells compared to normal control cells." (PMID 27590350, 2016). "This study investigates the potential anti-colorectal cancer (CRC) activity of IMT1, a novel specific inhibitor of mitochondrial RNA polymerase (POLRMT)." (PMID 39227564, 2024).
developmental delay (2 papers, 2021 to 2026). "Previously, pathogenic POLRMT, monoallelic de novo and recessively inherited biallelic, variants were reported in patients presenting with developmental delay, intellectual disability, hypotonia and short stature." (PMID 40583167, 2026). "However, the predominant clinical phenotype of the five paediatric patients harbouring POLRMT variants was an early onset moderate to severe developmental delay, mild to severe intellectual disability, hypotonia/muscle weakness, short stature, and speech delay." (PMID 33602924, 2021).
dilated cardiomyopathy (2 papers, 2021). Cardiomyopathy which is characterized by dilation and contractile dysfunction of the left and right ventricles. "POLRMT is the sole mitochondrial primase and its deletion leads to a profound decrease in mtDNA replication that is associated with severe mitochondrial dysfunction and dilated cardiomyopathy in POLRMT knockout mice." (PMID 33602924, 2021). "POLRMT is an essential gene, since knock-out (KO) mice are not viable due to embryonic lethality and conditional KO mice died after six weeks due to dilated cardiomyopathy." (PMID 34834357, 2021).
lung carcinoma (2 papers, 2021 to 2023). "Through GSEA, we found that high‐level expression of POLRMT was linked to MYC targets and Wnt/beta‐catenin signaling, both of which had a role in lung cancer cell processes and proliferation." (PMID 37283308, 2023). "TCGA cohorts show that POLRMT mRNA expression in lung cancer tissues is significantly higher than that in normal lung tissues." (PMID 34326320, 2021). "TCGA cohorts and the results from the local lung cancer tissues showed that POLRMT is overexpressed in human lung cancer tissues." (PMID 34326320, 2021). "The Cancer Genome Atlas (TCGA) cohorts showed a significantly high expression of POLRMT mRNA in lung cancer tissues (“Primary tumor”, n = 503)." (PMID 34326320, 2021). "Together, these results show that POLRMT is overexpressed in human lung cancer tissues and cells." (PMID 34326320, 2021).